CXCL10 (C-X-C motif chemokine ligand 10)
Diseases named in the same sentence as CXCL10 in open-access papers (continued):
Sharing a sentence is not in itself a finding about the gene and the disease.
melanoma (continued). "In a mouse model of spontaneous melanoma, both DTIC and TMZ have been shown to induce the secretion of chemokines such as CCL5, CXCL9, CXCL10 and CXCL11 by melanoma cells." (PMID 34712615, 2021). "The myPath Melanoma Test utilizes the expression of 14 signature genes, including PRAME, CXCL9, CXCL10, S100A7, S100A8, and S100A9, and nine reference genes to distinguish BN from CMM." (PMID 35008167, 2021). "As for anti-PD-1 blockade, the IFN-γ gene signature (IDO1, CXCL10, CXCL9, HLA-DRA, STAT1, and IFNG) predicts the response to anti-PD-1 therapy in multiple tumors, including melanoma." (PMID 34439264, 2021). "In line with ex vivo GBM slices, PVSRIPO-infection-induced CXCL10 and type-I/III IFN responses in breast cancer and melanoma tissue slices." (PMID 33767151, 2021). "CXCL9, CXCL10, and CXCL12 are important chemotactic factors in the TME, which are able to recruit T cells and increase inflammation in tumors such as melanoma and lung adenocarcinoma." (PMID 34497764, 2021). "Efficient traffic of cytotoxic T lymphocytes (CTLs) to metastatic sites in melanoma patients correlates with the expression of C-X-C Motif Chemokine Ligand 9 (CXCL9) and CXCL10 which are CXCR3 ligands." (PMID 32867162, 2020). "Peripheral blood mononuclear cells (PBMCs) secreted high levels of CXCL10, CCL2 and IFN-γ in response to co-culture with melphalan-exposed melanoma cells in vitro." (PMID 32002296, 2020). "It has been indicated in a mouse model of melanoma that T cell infiltration is enhanced by 18-fold in melanoma cells through inhibition of VEGF and consequently overexpression of CXCL10 and CXCL11 in tumor vessels." (PMID 32499786, 2020). "In an in vitro model aiming to mimic ILP, we observed that melphalan exposure triggered a pronounced induction of CXCL10, CCL2 and IFN-γ in melanoma/PBMC co-cultures." (PMID 32002296, 2020). "In another report, intratumoral injection of IFN-b also increased CD8+ TILs in melanoma by the induction of M1 macrophage-related chemokines (CXCL9, CXCL10, CXCL11), leading to enhancement of the anti-tumor effects of anti-PD1 Abs for melanoma in vivo." (PMID 32707850, 2020). "Functional studies revealed that blockade of CXCL9 and CXCL10, or their receptor CXCR3, impairs recruitment of adoptively transferred T cells into melanoma tumors." (PMID 30873179, 2019). "In this study, the B16 melanoma cells produced different levels of CXCL1, CXCL10, M-CSF, and CCL5 compared to the B16/BL6 cells." (PMID 30123429, 2018). "In a therapeutic setting for melanoma, adjuvant IFN-α therapy of melanomas is known to upregulate CXCL10 production while CXCL9 and CXCL10 were induced in melanomas by chemotherapy agents such as cisplatin." (PMID 30320116, 2018). "The CD103+ DCs elevated CXCL9 and CXCL10 in order to further attract T cells to infiltrate the tumor, and deletion of CCL4 in the melanoma cells abrogated T cell infiltration." (PMID 29109732, 2017). "Previously, we found that melanoma-activated TIL induced MSCs to produce a wide variety of chemokines including the Th1 chemokines CCL5, CXCL9, CXCL10 and CXCL11 and the Th1 cytokine IL-125." (PMID 27211104, 2016). "Since CXCL10/IP-10 was found strongly up-regulated at the mRNA level in both HUVEC and melanoma cells, we aimed at validating such modulation at the protein level." (PMID 27764787, 2016). "CXCL10 is involved in the recruitment of CD8+ T lymphocytes in breast cancer, colorectal carcinoma, melanoma, and hepatocellular carcinoma." (PMID 26317795, 2015). "CXCR3 expression in human and murine melanoma cell lines has been suggested by others to mediate directional cell migration along the chemokine gradients of CXCL9, CXCL10 and CXCL11." (PMID 21179030, 2011). "To further confirm that TuECs express high levels of CXCR3 ligands, we isolated LECs and blood endothelial cells (BECs) from normal human skin and TuECs from melanoma metastases and compared the expression levels of CXCL9 and CXCL10 using RT–PCR." (PMID 21179030, 2011).
melanoma (continued). "Furthermore, the receptors for CXCL10 and CXCR3 are upregulated in melanoma cells, with a predilection for the brain." (PMID 39780275, 2025). "Moreover, CLEC4A expression exhibited significant correlations with CXCL10 (r = 0.706) and LAT2 (r = 0.851), suggesting potential cooperative roles of these genes in melanoma." (PMID 40607411, 2025). "In addition, we found that IκBζ simultaneously repressed several chemokines such as Cxcl9, Cxcl10, and Ccl5 in D4M-3A, YUMM1.7, and B16-F10 melanoma in vivo." (PMID 40562773, 2025). "At least two-fold upregulation of CXCL9, CXCL10, and CXCL11 was observed in all cancer types including melanoma (n = 77), breast cancer (n = 40), brain cancer (n = 198), and lung cancer when comparing samples with high to low MOTIscores, with significance for melanoma and breast cancer." (PMID 41463470, 2025). "In patients with melanoma, endogenous secretion of CXCL9 and CXCL10 positively correlates with improved prognosis and overall response by induction of CD8+ T-cell recruitment to the tumor site and correlates with improved response to anti–PD-1 and anti–CTLA-4 blockade in vitro." (PMID 39867570, 2025). "In a melanoma mouse model, we demonstrated that Ackr2 inhibition increases the release of proinflammatory chemokines CCL5 and CXCL10 and enhances the infiltration of NK cells, activated CD8+ and CD4+ effector T cells while reducing regulatory T cells (Tregs) in the TME." (PMID 40248897, 2025). "There was a negative correlation tendency between Mi-2β and Cxcl9 and Cxcl10 at the mRNA level in melanomas in TCGA." (PMID 38461299, 2024). "As CXCL10 was amplified related to the induction of tumor angiogenesis during B16F10 melanoma tumor growth in vivo, we further investigated the effect of CXCL10 on expression of pro-angiogenic factors in B16F10 melanoma cells." (PMID 39268223, 2024). "Additionally, co-delivered nanovaccines increase the generation of pro-inflammatory cytokines by DCs, such as IFN-β, TNF-α, CXCL-9, and CXCL-10, which promote the proliferation and recruitment of antigen-specific CD8+ T cells in melanoma TME." (PMID 38185685, 2024). "Furthermore, we show that IFNγ stimulated dedifferentiated melanoma cells display increased secretion of CCL2, IL-10, CXCL10 and PD-L1 and increased PD-L1 expression on their cell membranes." (PMID 39736644, 2024). "In the current report, we showed a significant increase in CXCL10 production during the subcutaneous growth of B16F10 melanoma tumors, primarily originating from the host rather than from the melanoma tumor itself." (PMID 39268223, 2024). "Five genes (CXCL10, TNF, PIK3CD, PIK3R2, and CXCL1) of the TNF signalling pathway and seven genes (CXCL9, GDF15, BMP7, TNFRSF15, CXCL10, TNF, and CXCL1) of the cytokine–cytokine receptor pathway were commonly upregulated in melanoma cells." (PMID 39496484, 2024). "In this study, we found that CXCL10 induces CREB Ser133 phosphorylation in melanoma cells, which could be involved in VEGF upregulation to enhance melanoma angiogenesis." (PMID 39268223, 2024). "CXCL10 chemokine secreted by astrocytes has been shown to elevate the receptor CXCR3 expression in tumor cells, thereby boosting absorption and migration capacity of melanoma BM cells." (PMID 38104104, 2023). "Moreover, IFN-α and CXCL10 production by in vitro stimulated (i.e. with R848, CpG-A, ADU-S100) pDCs exposed to melanoma cell lines supernatants (SN-mel) was tested by intracellular flow cytometry and ELISA." (PMID 38239354, 2023). "Interestingly, a previous study detected elevated plasma CXCL9 and CXCL10 levels in mice that responded to ICI therapy, and similar results were recorded in patients with melanoma." (PMID 38133557, 2023). "Our work revealed that serum level of APRIL/TNFSF13, but not CCL19, CXCL10 or CXCL13 when considered as single analytes, was associated with improved event-free survival (EFS) in patients with melanoma." (PMID 37435077, 2023).
melanoma (continued). "In the melanoma sample (patient 16), CXCL9, CXCL10, CXCL11, and CXCL13 as well as tumor growth factor beta (TGF-β) were higher at the tumor periphery, indicating that T cells in this region are subject to a unique chemokine and cytokine milieu compared with those deeper within the tumor." (PMID 35584630, 2022). "Our results also support the link of melanoma with CCL4, CXCL10, and CCL510." (PMID 36443341, 2022). "Thus, in vitro experiments have shown that IFN-β treatment induced CXCL10 expression of melanoma cells and DCs stimulated with IFNα/IFN-β produced significant amounts of CXCL9 and CXCL10." (PMID 35626062, 2022). "Higher levels of CXCL9, CXCL10, and CXCL11 were also detected in melanoma patients’ tumors following treatment with ipilimumab, an antagonistic antibody against cytotoxic T-lymphocyte-associated protein 4 (CTLA4), another inhibitory receptor expressed by T cells." (PMID 33603130, 2022). "Besides revealing macrophages, some researchers have found that CXCL10 activates its receptor CXCR3 to induce the infiltration of CD8+ T cells in colorectal cancer, breast cancer, melanoma." (PMID 35083488, 2022). "PAI-1 decreased the production of CXCL10 and CCL22, suggesting that PAI-1 might decrease the TILs in melanoma." (PMID 34912726, 2021). "In syngeneic CT26 colorectal cancer and B16F10 melanoma mouse models, sitagliptin treatment enhanced CD4+ and CD8+ T cell infiltration and reduced tumor growth and metastases due to preservation of the active CXCL10 form." (PMID 34503058, 2021). "C1QB, CXCL9, CXCL10, DFNA5 (GSDME), FCGR1B, and PRAME were increased in melanoma, and SCGB1D2 was decreased in melanoma, compared to dysplastic nevi or nevi that progressed to melanoma." (PMID 35008167, 2021). "CXCL8, CXCL9, CXCL10, CCL27, and C3AR1 have known immunomodulatory roles in melanoma." (PMID 35008167, 2021). "Fluorescence imaging revealed that intravenously injected DiR-labeled NK cells migrated and infiltrated to melanoma expressing CXCL10 rather than to negative melanoma tumor." (PMID 32455886, 2020). "Expanded cells migrated strongly toward CXCL10-transfected melanoma, but not CXCL10-negative tumor cells." (PMID 33287875, 2020). "Baseline serum CXCL5, but not CXCL10 and CCL22, is associated with the efficacy of nivolumab in advanced melanoma." (PMID 32707850, 2020). "Notably, gene expression sequences from melanoma biopsies also revealed a positive correlation between CCL5, CXCL2, CXCL9, and CXCL10 and clinical benefit in a phase II trial of a MAGE-A3 vaccine." (PMID 30899263, 2019). "For example, in melanoma, the lack of CCR5 ligands (CCL3, CCL4, CCL5) and CXCR3 ligands (CXCL9 and CXCL10) has been associated with limited infiltration of antigen-specific T cells." (PMID 30873179, 2019). "Interestingly, tumor endothelial cells facilitate melanoma migration through their production of CXCL9 (and CXCL10)." (PMID 30420855, 2018). "Expression and binding of specific chemokine/chemokine receptors such as CXCR3-CXCL9/CXCL10 have been proposed as non-redundant requirements for endothelial transmigration of T cells across tumor vasculature in melanoma." (PMID 30126117, 2018). "Simultaneous expressions of CXCL10 and CXCR3 in breast cancer cell lines additionally lead to CXCL10-dependent proliferation of CXCR3-positive cells and treatments using CXCR3 antagonists, and ligand-neutralizing antibodies inhibit metastasis in melanoma and breast cancer in mice." (PMID 24395654, 2014). "Indeed, it has been shown that mouse melanoma B16F10 cells constitutively express CXCR3, and its ligands CXCL9/Mig, CXCL10/IP-10, and CXCL11/I-TAC induce cellular responses in vitro, such as actin polymerization, migration, invasion, and cell survival." (PMID 24559071, 2014).
melanoma (continued). "Increased IL-12, on the other hand, contributes to boost the innate immune response while the increase of the anti-angiogenic factor CXCL10 together with a decreased VEGF level counteracts neo-angiogenesis and thereby likely contributes to the observed shrinkage of the melanoma lesions." (PMID 22289880, 2012). "Lipopolysaccharides can stimulate normal human melanocytes to produce IL-1β, TNFα, IL-6, IL-8, CCL2, CCl3, and CCL5, and chemotherapy of melanoma-bearing mice results in enhanced expression of CCL5 and the CXCR3 ligands CXCL9, CXCL10, and CXCl11 by tumor cells." (PMID 22745913, 2012). "None of the treatments with 0–400 ng ml−1 CXCL9 or CXCL10 influenced cell death or cell proliferation in melanoma cells (data not shown)." (PMID 21179030, 2011). "In addition, DC pulsed with reovirus-infected melanoma cells secrete the chemokines CCL2, 3, 4, 5, 7, 8, 11 (eotaxin), and CXCL10 (IP-10), and these culture supernatants induce NK cell chemotaxis." (PMID 21338484, 2011). "Interestingly, the CXCL9/CXCL10 secretion increase was stronger after coadministration of GUA and MAPKi, suggesting a possible addictive interaction between these 2 compounds in regulating melanoma T helper 1 chemokine secretion." (PMID 39867570, 2025). "Thus, we hypothesized that IκBζ might repress CXCL9, CXCL10, and CCL5 expression through the interaction with EZH2 and/or HDAC3 in melanoma." (PMID 40562773, 2025). "To evaluate the significance of the direct effect of CXCL10-Fc on the ability of CXCR3+ CD4+ T cells to limit tumor growth, we performed an adoptive transfer in which CD4+ T cells were isolated from OT-II mice engrafted with Ret melanoma, transferred into CXCR3KO mice." (PMID 39474427, 2024). "Dedifferentiation renders 624Mel melanoma cells hypersensitive to IFNγ stimulation in a context-dependent manner, resulting in non-additive upregulation of IFNγ-induced genes, increased PD-L1 protein expression and amplified secretion of CCL2, CXCL10 and IL-10." (PMID 39736644, 2024). "Hence, this small pilot study supports a paradigm for studying expression of a 3 TLS-kine index (APRIL/TNFSF13, CXCL10 and CXCL13) in serum that may predictive presence of histologically defined LA and/or TLS in the TME of melanoma patients." (PMID 37435077, 2023). "Clinically, it has been shown that elevated pre-treatment CXCL9 and CXCL10 levels correlate with the response to anti-PD-L 1 therapy in patients with non-small cell lung cancer, and CXCL9 and CXCL10 increase in the first months of treatment in melanoma patients responding to PD-1 inhibitor therapy." (PMID 37569757, 2023). "Given the important role of CXCL10 in regulating CXCR3+ T cell trafficking into tumors, we next tested whether demethylation-mediated rescue of STING signaling in STINGlow B16-F10 melanoma models could restore melanoma-intrinsic CXCL10 induction." (PMID 36949064, 2023). "Immune-profiling and cell depletion experiments revealed that melanoma cell-derived Activin-A reduces the dependence on suppressive CD4+ T cells to escape immune surveillance, correlating with the diminished secretion of specific chemokines such as CXCL9 and CXCL10." (PMID 35580932, 2022). "A study of individual CSF samples from 22 patients with melanoma brain metastases and 5 disease-free controls found that Chemokine CCL22 and cytokines IL-1α, IL-4, and IL-5 were reduced in most samples, whereas a subset of molecules including CXCL10, CCL4, CCL17, and IL8 increased expression." (PMID 36527157, 2022). "Indeed, systemic administration of IFNγ increased levels of CXCL10 and intratumoral T cell infiltration in a phase 0 clinical trial for sarcoma, and intratumoral injection of IFNγ increased tumor CXCL10 and CXCL11 in melanoma patients." (PMID 33603130, 2022).
melanoma (continued). "Further, analysis of clusters identified within the melanoma patient set comparing patient outcome suggests that suppression of IL-1α, IL-4, IL-5, and CCL22, with concomitant elevation of CXCL10, CCL4, and CCL17, may correlate with more aggressive development of brain metastasis." (PMID 36527157, 2022). "I-BET151 inhibits NF-kB activation in melanoma by targeting BRD2, causing cycle arrest, promoting apoptosis, and inhibiting the production of cytokines (e.g., IL6 and IL-8) and chemokines (e.g., CXCL10 and CCL5), which indicates that I-BET151 may have a therapeutic effect on melanoma." (PMID 34540687, 2021). "Moreover, IFNγ signatures (CXCL10, CXCL9, IDO1, IFNG, and STAT1) and myeloid lineage phenotypic and functional markers (CD14, CD163, CD33, and CD68) were also significantly increased in melanoma patients with high ETV7." (PMID 33424867, 2020). "The CXCL9, CXCL10, and CXCL11/CXCR3 axis was generally considered to have antiangiogenic effects on endothelial cells and has been reported as effective tumor angiogenesis inhibitors in some in vivo tumor models, including pancreatic cancer, breast cancer, lung cancer, and melanoma." (PMID 32685487, 2020). "In addition, expression and binding of specific chemokine/chemokine receptors such as CXCR3-CXCL9/CXCL10 have been proposed as non-redundant requirements for endothelial transmigration of T cells across tumor vasculature in melanoma." (PMID 30126117, 2018). "Moreover, in melanoma enhanced CXCL9 and CXCL10 correlated with reduced metastasis." (PMID 29379506, 2017). "Notably, TAM-related chemokines, such as CXCL5, CXCL10, and CCL22, as well as a TAM-activation marker, soluble (s)CD163, could be predictive markers for efficacy and immune-related adverse events (irAEs) in anti-PD1 Abs-treated advanced melanoma patients." (PMID 34912726, 2021). "Although the chemokines CXCL9, CXCL10 and CXCL11 were reported to have an angiostatic effect when expressed by melanoma cells, our study suggests that the chemokine CXCL9 may promote additional metastasis, when it is expressed in TuECs, by means of increasing transendothelial and melanoma migration." (PMID 21179030, 2011). "Moreover, a cohort study in melanoma tissues revealed negative associations between intratumoral members of the genera Algibacter and Epilithonimonas and CD8+ T cell infiltration, while the Algibacter genus was also negatively correlated with overexpression of the chemokines CXCL9, CXCL10 and CCL5." (PMID 39120310, 2024). "In melanoma BM patients, the CSF levels of IL-1α, IL-4, IL-5 and CCL22 significantly decrease while those of CXCL10, CCL4 and CCL17 significantly increase compared to non-disease group." (PMID 35884845, 2022). "First, the inhibition of the dipeptidylpeptidase DPP4 dampens the CXCL10 degradation, thus improving the CD4 and CD8 T-cell recruitment and limiting the melanoma and colon tumor growth in the presence or not of anti-PD-1 and/or anti-CTLA-4." (PMID 36429101, 2022). "Unlike CXCL5, baseline serum concentrations of CXCL10 and CCL22 have not shown any correlations with the efficacy of nivolumab against advanced melanoma." (PMID 31417907, 2019). "Induction of STING expression in 5AZADC-treated melanoma cell lines lacking STING and production of CXCL-10 following their stimulation with the STING agonist suggested DNA hypermethylation involvement in cases where STING gene mutations were absent." (PMID 30400822, 2018). "Melanomas developed from cells lacking MyD88 showed an enhanced secretion of chemoattractant ligands such as CCL2, CXCL10 and CXCL1 and have an improved infiltration of macrophages to the tumor site." (PMID 28662055, 2017). "CXCL9, CXCL10, PD-L1, CD86, IL-10, TREM2, GPNMB, IL-4l1 and FOLR2 markers showed widespread expression by most melanoma TAMs, with no definition of a particular macrophage subset, and regardless of whether the tumor was metastasizing or not." (PMID 40406129, 2025).
melanoma (continued). "Also, in another scientific study that analyzed plasma samples from 28 patients with advanced melanoma who were treated with pembrolizumab and nivolumab plus ipilimumab, responders (n = 18) had a greater quantity of CXCL9 and CXCL10 compared to non-responders (n = 10)." (PMID 39273452, 2024).